HMG20B (high mobility group 20B)
Description:
Required for correct progression through G2 phase of the cell cycle and entry into mitosis. Required for RCOR1/CoREST mediated repression of neuronal specific gene promoters.
Synonyms: BRAF35; HMGX2; HMGXB2; SMARCE1R; SOXL; BRAF25; PP7706; pp8857
Tractability: PROTAC: UniProt records ubiquitination sites on it; ubiquitination databases record sites on it; its protein half-life has been measured.
Gene: Protein-coding gene on chromosome 19 (3,572,741 to 3,579,088, forward strand). Ensembl gene ENSG00000064961.
Subcellular location: Nucleus; Chromosome
Subcellular location (Human Protein Atlas): Nucleoplasm
Pathways (Reactome):
Chromatin organization: HDACs deacetylate histones
Disease: Potential therapeutics for SARS
Hemostasis: Factors involved in megakaryocyte development and platelet production
Gene Ontology:
Molecular function: protein binding
Biological process: regulation of gene expression
Cellular component: nucleoplasm; nucleus; chromosome
Genetic constraint (gnomAD): Loss-of-function variants: 24 observed, 31.04 expected, observed/expected ratio (o/e) 0.77, 90% interval 0.56 to 1.09. The synonymous counts are far from expectation, so gnomAD's model fits this gene poorly and the ratio says little. Missense variants: 461 observed, 375.84 expected, observed/expected ratio (o/e) 1.23, 90% interval 1.14 to 1.33. Synonymous variants: 251 observed, 167.05 expected, observed/expected ratio (o/e) 1.5, 90% interval 1.36 to 1.67.
Homologues: Orthologues: chimpanzee HMG20B (100% identical), macaque HMG20B (99% identical), pig HMG20B (97% identical), guinea pig HMG20B (95% identical), mouse Hmg20b (94% identical), rat Hmg20b (94% identical), dog HMG20B (82% identical), tropical clawed frog hmg20b (72% identical), zebrafish hmg20b (58% identical), Caenorhabditis elegans hmg-3 (10% identical), Caenorhabditis elegans hmg-4 (10% identical). Paralogues in human: HMG20A (47% identical), SMARCE1 (25% identical), TOX3 (20% identical), TOX4 (18% identical), TOX2 (16% identical), TOX (16% identical), UBTF (15% identical), HMGXB4 (14% identical), SP100 (14% identical), HMGB3 (13% identical), HMGB2 (13% identical), HMGB1 (13% identical), and 8 more.
Diseases named in the same sentence as HMG20B in open-access papers:
HMG20B is named in the same sentence as 18 diseases in open-access papers, as found by Europe PMC text mining. Sharing a sentence is not in itself a finding about the gene and the disease. The quoted sentences say what the papers report.
glioma (2 papers, 2022 to 2024). A benign or malignant brain and spinal cord tumor that arises from glial cells (astrocytes, oligodendrocytes, ependymal cells). "The RT-qPCR assay showed that the six signature genes (TRIM24, IDH1, LBR, HMG20B, USP49, and RCC1) were up-regulated in glioma cell lines in mRNA expression level." (PMID 36246611, 2022). "Our study suggests that TRIM24, IDH1, LBR, HMG20B, USP49 and RCC1 were all highly expressed in glioma tissues and gliomar cell lines both at the mRNA and protein level." (PMID 36246611, 2022).
lung carcinoma (2 papers, 2014 to 2019). "These mutations occur in several different forms of human epithelial cancer, including lung carcinomas, and affect a single HMG20B allele, prompting questions as to whether they affect HMG20b function despite the presence of a normal allele." (PMID 25486196, 2014). "The non-conservative substitution of HMG20b residue Ala247 with Pro, reported in human lung cancer, disrupts these activities of HMG20b, impairing cytokinesis in a trans-dominant manner." (PMID 25486196, 2014). "Interestingly, a non-conservative substitution of Ala247 to Pro within this critical HMG20b region, recently reported in human lung cancer, suffices to inactivate these activities of HMG20b." (PMID 25486196, 2014).
melanoma (2 papers, 2023 to 2025). A malignant, usually aggressive tumor composed of atypical, neoplastic melanocytes. "Among them, 6 genes (NPTX1, AUTS2, RPS6KA2, KAT2B, MYO5A and HMG20B) were simultaneously downregulated in the melanoma samples compared with the noncancerous samples in GSE31909 and GSE35388 microarray data." (PMID 37384727, 2023).
breast carcinoma (1 paper, 2014). "Many researchers suggest that breast cancer susceptibility gene 2 and Hmg20b complex may have a role in cell cycle regulation and affect cell fate determination." (PMID 25402494, 2014).
follicular lymphoma (1 paper, 2025). Follicular lymphoma is a form of non-Hodgkin lymphoma characterized by a proliferation of B cells whose nodular structure of follicular architecture is preserved. "Furthermore, a four-gene panel comprising CNN2, HMG20B, ACRBP, and IZUMO1 successfully distinguished DLBCL from follicular lymphoma (FL), achieving an AUC of 0.89 in the testing set, regardless of the cell-of-origin or stage of DLBCL." (PMID 40055844, 2025).
leukemia (1 paper, 2022). A malignant (clonal) hematologic disorder, involving hematopoietic stem cells and characterized by the presence of primitive or atypical myeloid or lymphoid cells in the bone marrow and the blood. "We made use of gene set enrichment analysis (GSEA) to confirm that HMG20B KD induced expression of a leukemia cell differentiation program." (PMID 36171271, 2022). "Functional assays demonstrated that HMG20B depletion induces leukemia cell differentiation and further revealed that HMG20B is required for the transcription repressor activity of GFI1 through stabilizing LSD1 on chromatin at GFI1 binding sites." (PMID 36171271, 2022). "In keeping with induction of a leukemia cell differentiation program we also noted that HMG20B KD resulted in strong depletion of a gene set which promotes leukemia stem cell maintenance in murine MLL-AF9 AML cells." (PMID 36171271, 2022). "Thus, HMG20B is a critical component of the GFI1:LSD1 transcription repressor complex which contributes to leukemia cell differentiation block." (PMID 36171271, 2022).
Merkel cell carcinoma (1 paper, 2022). "In Merkel cell carcinoma, an aggressive neuroendocrine carcinoma of the skin, LSD1 inhibition derepresses key regulators of the neuronal lineage via the disruption of LSD1-CoREST complex integrity, including induction of HMG20B degradation." (PMID 36171271, 2022).
myeloid leukemia (1 paper, 2022). A clonal proliferation of myeloid cells and their precursors in the bone marrow, peripheral blood, and spleen. "Our studies reveal the coincident genome-wide binding of the HMG-box protein HMG20B with LSD1 and GFI1 in myeloid leukemia cells, and the functional relevance of the interaction of the coiled-coil domain of HMG20B with LSD1 in stabilizing the interaction of LSD1 with GFI1." (PMID 36171271, 2022).
prostate carcinoma (1 paper, 2007). A carcinoma that arises from epithelial cells of the prostate gland. "Altered expression of HMG20B has previously been reported in prostate cancer." (PMID 17280610, 2007). "Intriguingly, two genes (BCCIP, HMG20B) appeared in our analysis that interact with BRCA2, another, albeit weaker candidate for a hereditary prostate cancer gene." (PMID 17280610, 2007).
cancer (3 papers, 2014 to 2026). A tumor composed of atypical neoplastic, often pleomorphic cells that invade other tissues. "Here, we identify a carboxyl (C)-terminal region of the high-mobility group protein HMG20b that is essential for cytokinesis, and report that it is inactivated by a cancer-associated mutation." (PMID 25486196, 2014). "Together, these results strongly suggest that the cancer-associated A247P mutation is not only functionally deleterious, but also that it can induce cytokinesis failure and aneuploidy in a dominant manner even when wild-type HMG20b is also present." (PMID 25486196, 2014). "Of note, It was revealed that the expression of most genes was generally consistent with results of TCGA cancer set, such as TRIM24, HMG20B, CBX6, IDH1, RCC1, RYBP, CBX7, and LBR." (PMID 36246611, 2022).
tumor (3 papers, 2015 to 2024). "Among these 10 genes HDAC1, CASP3, REST, HMG20B, FZD7,GNAI3, FZD1 and EPHB4 had elevated expression in tumor group compared to the normal group, while KCNJ9 and SCRT1 were decreased." (PMID 38629068, 2024).
HMG20B also shares sentences with these, for which no sentence is quoted: ablepharon macrostomia syndrome (1 paper); anemia (1); Barber-Say syndrome (1); Coffin-Siris syndrome (1); colorectal cancer (1); Intellectual disability (1); skin cancer (1).